HMGA1 (high mobility group AT-hook 1)
Diseases named in the same sentence as HMGA1 in open-access papers (continued):
Sharing a sentence is not in itself a finding about the gene and the disease.
tumor (continued). "Of note, tumors arising from cells with HMGA1 knockdown included a subset of tumor cells with HMGA1 intranuclear staining resembling controls, consistent with our gene expression data suggesting that escape from HMGA1 silencing allows tumor cells to grow as xenografts." (PMID 36919699, 2023). "HMGA1 has been reported to be a potential tumor promoter in LIHC32,33; however, its interaction with miRNAs in a ceRNA role remains unclear." (PMID 36635290, 2023). "Silencing either HMGA1 or FGF19 disrupts phenotypes required for tumor progression." (PMID 36919699, 2023). "Together, these findings suggest that HMGA1 fosters tumor progression through both cell-intrinsic and stromal interactions, though little is known about transcriptional networks and tumor-stroma crosstalk governed by HMGA1 in PDAC." (PMID 36919699, 2023). "Although BLU9931 resulted in slightly lower mean tumor volumes in KPC/Hmga1 heterozygous implants in addition to decreased HMGA1, FGF15, and Ki-67 staining, and 2 of 3 CAF subtypes, the changes were modest, as tumor growth was markedly diminished by Hmga1 haploinsufficiency alone." (PMID 36919699, 2023). "Together, we discovered what we believe is a previously undescribed paradigm whereby tumor cells collaborate via HMGA1 and FGF19 to drive progression, thus illuminating FGF19 as a rational therapeutic target for a molecular subclass composed of the most aggressive human PDACs." (PMID 36919699, 2023). "HMGA1 may affect tumor progression by suppressing the infiltration of neutrophils and Th17 cells, promoting the expression of immune inhibitors and interacting with other signaling pathways." (PMID 36705364, 2023). "The carcinogenesis and tumor progression pathways regulated by HMGA1 were explored." (PMID 36705364, 2023). "Analysis of these public datasets showed that HMGA1 is highly expressed in iCCA, suggesting that HMGA1 may play a role in tumor progression." (PMID 36978140, 2023). "Here, we uncover what we believe is a previously unknown epigenetic program whereby HMGA1 upregulates transcriptional networks involved in proliferation and tumor-stroma interactions during tumor progression and development of a fibroblastic stroma in PDAC." (PMID 36919699, 2023). "Because our primary goal is to identify actionable mechanisms in PDAC, we determined whether targeting the HMGA1/FGF19 pathway with BLU9931 mitigates tumor and stroma formation." (PMID 36919699, 2023). "As no experiments have been conducted to date in normal, non-malignant progenitor germ cells, we cannot be sure how the antiproliferative HMGA1-mediated effect of metformin could be similar to that observed in tumor cells." (PMID 37765126, 2023). "Silencing HMGA1 disrupts oncogenic properties and depletes tumor-initiating cells." (PMID 36919699, 2023). "Thus, the HMGA1 expression level was evaluated by real-time PCR method in postoperative tumor tissue and blood samples collected at the time of diagnosis, 100 days and 1 year after surgery from 47 NSCLC patients." (PMID 35948739, 2022). "We found that the HMGA1 expression in the blood tends to decrease after surgical removal of the NSCLC tumor that could suggest tumor cells are the substantial source of HMGA1 expression measured in the blood." (PMID 35948739, 2022). "In patients with endometrioid endometrial carcinoma, high HMGA1 expression was associated with histological grade and tumor size as negative prognostic factors influenced by HMGA2." (PMID 35629376, 2022). "HMGA1 is defined as an oncofetal protein since it is highly expressed during embryogenesis, its expression decreases to very low levels or it is absent in adults but then it is overexpressed in a variety of tumours." (PMID 35504904, 2022). "HMGA1 can also enhance the aggressiveness of tumor cells through the HMGA1-MMP-2 pathway." (PMID 36253800, 2022).
tumor (continued). "Additionally, AC elevated the expressions of miR-635, E-cadherin, GRP78, and Chop and inhibited Ki-67, HMGA1, N-cadherin, and hnRNPA1 expressions in tumor tissues of mice." (PMID 35692504, 2022). "Another study in 2021 found that HMGA1 promotes xenograft tumor growth and radioresistance in CHOL." (PMID 35040749, 2022). "HMGA1 expression positively correlated with tumour aggressiveness in TNBC." (PMID 35267409, 2022). "Finally, we show in an in vivo xenograft model that depletion of HMGA1 chemo-sensitizes tumour cells to paclitaxel, a drug that is commonly used in TNBC treatments." (PMID 35504904, 2022). "In addition to the expression of HMGA1 during normal development, HMGA1 is overexpressed in most malignancies, Furthermore, the malignant degree of tumours, chemotherapy resistance and drug sensitivity are related to the expression level of HMGA1." (PMID 35864955, 2022). "Last but not the least, IHC assay provided that knockdown of circ-LIMK1 or DDP treatment could reduce the expression of Ki67 and HMGA1 in tumor tissues, and Ki67 and HMGA1 were lowest after knockdown of circ-LIMK1 and treatment with DDP." (PMID 36304135, 2022). "Both LINC00665 and circ 0067835 also upregulate HMGA1 to promote tumour progression." (PMID 35864955, 2022). "However, limited information is available about the link between HMGA1 and the tumor immune microenvironment." (PMID 35785026, 2022). "Our findings reported that depletion of HMGA1 in a xenograft mouse model sensitizes BC cells to paclitaxel, which would indicate that taxol-based applications may be more effective in reducing the tumour burden when tumour cells express low levels of HMGA1." (PMID 35504904, 2022). "Moreover, the expression of HMGA1 can affect tumor proliferation, apoptosis, angiogenesis, and N-cadherin and fibronectin expression, possibly through pAkt or pERK." (PMID 35629376, 2022). "HMGA1 has been reported to be highly expressed in GC and can promote tumor cell growth." (PMID 35014092, 2022). "In EWS, when HMGA1 was repressed by miR-214-3p, cells showed decreased cell growth and migration, indicating that the suppression of miR-214-3p may allow HMGA1 to play a role in sustaining tumor aggressiveness." (PMID 35406534, 2022). "Here, we analyzed the data from online datasets to compare the expression of HMGA1, and found higher expression was observed in 1085 tumor tissues when compared with 112 normal tissues, indicating that it might be a novel oncogene." (PMID 36479041, 2022). "The results indicated that cZRANB1 may promote tumor invasion by competing for the miRNAs with HMGA1, thereby increasing the expression level of HMGA1." (PMID 36132143, 2022). "At the same time, western blot analysis confirmed that knockdown of circ-LIMK1 could decrease the protein level of HMGA1 in tumor tissues and the tumor tissues after treatment with DDP." (PMID 36304135, 2022). "HMGA1 is an important part of the progression of most tumours." (PMID 35864955, 2022). "Tumor HMGA1 expression level was associated with neither features nor the overall survival of NSCLC patients." (PMID 35948739, 2022). "Moreover, HMGA1 has been shown to activate a variety of genes involved in tumorigenesis, tumor proliferation, migration, invasion, and epithelial-mesenchymal transition." (PMID 33648560, 2021). "Collectively, lncRNA TTN-AS1 acted as a tumor promoter in GBC by regulating miR-107/HMGA1 axis." (PMID 34090483, 2021). "Furthermore, HUCCT1 and QBC939 cells with HMGA1 overexpression were also subcutaneously injected into nude mice (n = 5) and forced expression of HMGA1 induced a significant increase in tumor mass and volume in xenografts of both cell lines." (PMID 34716319, 2021). "And HMGA1 exacerbated tumor growth and accelerated migration/invasion in cervical cancer." (PMID 34090483, 2021). "Together, these findings suggest that HMGA1 could foster tumor progression through both cell-intrinsic and cell-extrinsic or stromal interactions." (PMID 34572547, 2021).
tumor (continued). "On the other hand, it has been reported that microRNA-758 simultaneously suppresses HMGA1 and Wnt/β-catenin when it inhibits tumor cell growth, suggesting that the HMGA1/Wnt/β-catenin system may also be involved in the growth and invasion of EVTs." (PMID 34072941, 2021). "Cell viability assay and a xenograft model showed that HMGA1 overexpression could reverse the anti-tumor effect of hsa_circ_0091994 knockdown in GC." (PMID 34483139, 2021). "Bioinformatics analysis showed that HMGA1 was highly expressed in GC tumor tissue." (PMID 34483139, 2021). "Additional studies are needed, but our observation that GC patients with high levels of HMGA1 expression in the tumor benefit more from being treated with chemotherapy, should advise the selection of these patients for treatment, with expected improvements of their overall survival." (PMID 35049679, 2021). "HMGA1 (i.e., upregulated in tumor MF) and PTPN11/SHP2 (i.e., downregulated in MF) were selected." (PMID 34831413, 2021). "If so, this would be a great breakthrough of HMGA1-induced tumor stemness." (PMID 33648560, 2021). "HMGA1 is an architectural transcription factor, and it is involved in a number of tumour processes." (PMID 33169939, 2020). "HMGA1 is an oncofoetal protein that participates in tumourigenesis and tumour progression." (PMID 30614613, 2019). "The establishment of an HMGA1-RAGE pathway could help to clarify the complex array of cellular processes mediated by RAGE in tumor cells." (PMID 31779212, 2019). "Therefore, based on our results, we considered that an autocrine loop of HMGA1-RAGE was responsible for increased mobility of tumor cells, and therefore an enhanced migratory ability." (PMID 31779212, 2019). "Our work went a step beyond and proposed that not only the overexpression but also the subcellular localization of HMGA1 could help as a tumor progression biomarker." (PMID 31779212, 2019). "The correlation between HMGA1 and MMP9 expression in late stage EEC samples raises the hypothesis that the upregulation of HMGA1 may trigger tumor invasiveness through MMP9 upregulation and consequently lead to patients’ poorer prognosis." (PMID 31096664, 2019). "It will be important to test whether chromatin structure is altered in the stroma of such tumours and whether this is dependent on HMGA1 repression." (PMID 29743479, 2018). "Further characterization of this oncogenic regulatory mechanism may uncover a novel therapeutic intervention point for tumours driven by HMGA1." (PMID 30405205, 2018). "These proteins could be considered at the base of the HMGA1–dependent pyramidal cascade of events and early involved in tumor cell dissemination." (PMID 28924209, 2017). "Induction of IL-24 expression in the tumor cells markedly reduced HMGA1 mRNA and protein levels." (PMID 27602961, 2016). "Indeed, HMGA1P1 is mutated at position 25 where a tryptophan residue substitutes an arginine, within the first AT-hook of HMGA1, which has been shown to be a major site of modification in tumor cells." (PMID 26895108, 2016). "Strikingly, when integrating the transcriptome under HO-1 modulation with the HO-1 interactome, a framework of four main molecular pathways arose as the foundation for the regulation of the tumor cell protrusive forces: ANXA2/HMGA1/POU3F1; NFRSF13/GSN; TMOD3/RAI14/VWF; PLAT/PLAU." (PMID 28032857, 2016). "Similarly, RT-PCR with the primer set HMGA1–284F1/HMGA1–648R1 amplified a HMGA1 cDNA fragment indicating that the HMGA1 gene was expressed in the tumor (lane 8)." (PMID 25621995, 2015). "Overall, we speculated then that CRMP1 is negatively regulated by HMGA1 and it is functionally important in MB tumor biology." (PMID 26009886, 2015). "In fact, 55.5% and 44.4% of tumor samples with a weak HMGA1 staining (1+) had negative or weak staining also for BUBR1 and TTK respectively, whereas 61.5% and 66.7% of tumor samples with a strong HMGA1 immunoreactivity (3+) had also a strong immunoreactivity for BUBR1 and TTK, respectively." (PMID 26009897, 2015).
tumor (continued). "Recently, several miRNAs have been demonstrated to target these genes, and their dysregulation may contribute to HMGA1 protein overexpression in human neoplasias." (PMID 25268743, 2014). "Moreover, HMGA1-silencing promotes gemcitabine-induced cytoxicity and reduces tumor growth in vivo in a nude mouse xenograft model of pancreatic cancer." (PMID 25409711, 2014). "HMGA2 could potentially serve as tumour marker in both species while HMGA1 might play a minor role in OSCC progression." (PMID 25245141, 2014). "The interactions show that the tumor suppressor miRNAs (miR-29a, miR-16, miR-125, and let-7) that could target the oncogene HMGA1 are downregulated." (PMID 24564251, 2013). "We observed that HMGA1 may inhibit the putative tumor-suppressor IRF1 (as per the interaction network) and that the miR-155 pro-oncomiR directly targeted IRF1." (PMID 24564251, 2013). "Notably, we showed that HMGA1 induces STAT3 expression in lymphoid tumorigenesis, and STAT3 inhibitors are cytotoxic to the HMGA1-driven tumor cells." (PMID 23658826, 2013). "This group also found that HMGA1 induces changes in classes of genes involved in tumor progression." (PMID 23658826, 2013). "Notably, we found that 14 of 21 control mice displayed lymph node metastasis at this site, whereas only 2 of 21 mice carrying HMGA1-depleted tumours were macroscopically positive (left)." (PMID 23945276, 2013). "We next examined the impact of HMGA1 on tumour growth and metastatic dissemination in vivo." (PMID 23945276, 2013). "To address the hypothesis that the transcriptional programme induced by HMGA1 contained genes that are important for tumour aggressiveness, we initially utilised the Oncomine web tool." (PMID 23945276, 2013). "Furthermore, other tumor markers, such as Ki67 LI, mitoses counts and epithelioid cell pattern, which we found to be correlated with high HMGA1 expression levels in this study cohort, were also strongly correlated with metastatic mortality." (PMID 23935884, 2013). "We also discovered that germ cell tumor cells express less HMGA1 than fully reprogrammed iPSCs and hESCs, suggesting that a critical level of HMGA1 may be required for a fully reprogrammed, pluripotent, stem-like phenotype in contrast to a malignant phenotype." (PMID 23166588, 2012). "Moreover, tumors overexpressing HMGA1 and eight other ES transcription factor genes had decreased survival, underscoring the importance of these genes in tumor progression." (PMID 22276142, 2012). "The precise molecular pathways regulated by HMGA1 in transformation, however, are only beginning to emerge and studies to elucidate HMGA1 transcriptional networks are likely to uncover fundamental pathways involved in tumor progression and development." (PMID 22276142, 2012). "Furthermore, inhibiting HMGA1 expression blocks not only transformation properties involved in tumor initiation (anchorage-independent cell growth, tumorigenicity), but also cellular characteristics that promote metastatic progression (invasion and migration)." (PMID 22276142, 2012). "Our studies reveal distinct pathways activated by HMGA1 at different stages in tumor development." (PMID 22053823, 2011). "Future studies are needed to assess the functional status of these tumor suppressors in the HMGA1 transcriptional networks and are likely to uncover additional pathways that could be targeted in hematologic and other malignancies driven by HMGA1." (PMID 22053823, 2011). "Furthermore, the reverse correlation between let-7 downregulation and HMGA1 overexpression has been first observed in tumours." (PMID 19156147, 2009). "HMGA1 expression showed a strong positive correlation with stemness indices derived from RNA expression (RNAss) and DNA methylation (DNAss) in the majority of tumor types, particularly BRCA, LUAD, and STAD, indicating its association with de-differentiated tumor states." (PMID 41463532, 2025).
tumor (continued). "Moreover, in addition to tumor tissues, HMGA1 and ISG15 were also upregulated in hepatic and renal steatosis, suggesting a correlation between fat accumulation and HMGA1‐ISG15 levels may exist in multiple tissues and diseases." (PMID 40126377, 2025). "Second, Hmga1 knockout in the context of ApcMin with ETBF, reduced tumor number, regardless of whether the HMGA1 deficiency was global or specific to the intestinal epithelium." (PMID 39895631, 2025). "Thus, the expression of HMGA1 by tumor derived epithelial cells may influence the tumor immune microenvironment (TIME)." (PMID 41145488, 2025). "High mobility group protein A1 (HMGA1) binds to AT-rich DNA regions and regulates various fundamental cellular processes at the molecular and cellular levels, including cell cycle regulation, embryonic development, tumor transformation, cell proliferation and differentiation." (PMID 38430408, 2024). "Because HMGA1 proteins are detectable only in late-stage precursor lesions (pancreatic intraepithelial neoplasia [PanIN] 3) or invasive tumors, this mechanism may be relevant later in carcinogenesis when tumor cells invade and metastasize." (PMID 36919699, 2023). "We hypothesized that circ_002136 interference could sensitize Tax-resistant GC cells to Tax through the miR-16-5p/HMGA1 axis and inhibit the growth and metastasis of Tax-resistant tumor cells, which may provide a new avenue for the treatment of patients with Tax-resistant GC." (PMID 36760722, 2023). "In addition, RT-qPCR analysis of the RNA level of HMGA1 showed that HMGA1 expression was up-regulated in tumor tissues compared with normal tissues (n = 56/group), the expression of HMGA1 was boosted in resistant tumor tissues (n = 37) compared with sensitive tumor tissues (n = 19)." (PMID 36304135, 2022). "When HMGA1 is silenced, there is a certain relationship between the activation of caspase 3 and the apoptosis induced by gemcitabine 105, and after HMGA1 overexpression, it can enhance the tumour invasion ability through Akt-dependent regulation of MMP-9 activity." (PMID 35864955, 2022). "In addition, HMGA1 is related to the chemoresistance of tumours." (PMID 35864955, 2022). "Moreover, blood HMGA1 mRNA level could decrease in time after tumor resection and could be connected with the survival of patients." (PMID 35948739, 2022). "Moreover, our data suggest that taxol-based treatments may be more effective in reducing the tumour burden when tumour cells express low levels of HMGA1." (PMID 35504904, 2022). "Furthermore, the result of immunofluorescence showed that talazoparib could increase the expression of p21 and Hmga1, reduce telomerase activity conversely in tumour tissue, suggesting that talazoparib promote tumour cell senescence." (PMID 32243714, 2020). "Previous reports showed that HMGA1 could affect tumor metastasis through a variety of ways." (PMID 31196036, 2019). "In accordance with this hypothesis, HMGA1 could be increasingly expressed along tumor evolution." (PMID 31737655, 2019). "By epigenetic reprogramming and regulation of gene networks—comprising OCT4 and cMYC—HMGA1 has been shown to maintain a pluripotent, undifferentiated state in embryonic stem cells, a mechanism by which the protein likely also contributes to cancerogenesis and tumor growth." (PMID 26117853, 2015). "Moreover, using a cell dispersion assay to simulate in 2D the metastatic dispersion of cells from the primary tumour, we observed that HMGA1-depleted cells grow in a monolayer as well-defined colonies, while control cells move individually, breaking the colony boundaries." (PMID 23945276, 2013). "Therefore, upregulation of HMGA1 plays a significant role in tumor progression in NSCLC." (PMID 24564251, 2013). "Thus, HMGA1 could promote tumor progression by inducing a molecular program for cell cycle progression and proliferation with up-regulation of E2F1 and cyclins." (PMID 22053823, 2011).